CXCR4 (C-X-C motif chemokine receptor 4)
Diseases named in the same sentence as CXCR4 in open-access papers (continued):
Sharing a sentence is not in itself a finding about the gene and the disease.
neuropathy (11 papers, 2012 to 2024). A disorder affecting the nervous system that manifests with pain, tingling, numbness, and/or muscle weakness. "For instance, blockade of CXCR4 signaling by its antagonist AMD3100 reversed the maintenance of neuropathic pain induced by either chronic constriction injury (CCI) of the sciatic nerve or HIV-associated neuropathy." (PMID 22998838, 2012). "Recently we reported on the first 3 patients with anti-MAG antibody neuropathy and WM (MYD88L265P mutation and wild-type CXCR4 gene), treated with ibrutinib." (PMID 35349079, 2022). "Preliminary positive data on the BTK inhibitor, ibrutinib, in patients with anti-MAG antibody neuropathy and a specific mutational profile (MYD88L265P mutation, wild-type CXCR4 gene) need further confirmation on larger populations." (PMID 35349079, 2022). "The level of chemokine receptor CXC receptor 4 (CXCR4) is increased in the peripheral neurons of diabetic patients with neuropathy, which demonstrates a similar and crucial role for CXCR4 in the neurons of sufferers with DNP." (PMID 35799894, 2022). "Recent studies on the pathophysiological mechanisms of CXCL12/CXCR4 axis in the pathogenesis of pain by various nerve injury and neuropathy models, including diabetic neuropathy, demonstrate the axis as a promising pharmacological target." (PMID 32019145, 2020). "Essentially, this CXCR4 antagonist was also effective in alleviating mechanical allodynia when pSNL-induce neuropathy had been established." (PMID 25119456, 2014). "To better explore the maintenance of chemotherapy-induced neuropathic pain and its modulation by CB2 agonists, we investigated the possible contribution of the alpha-chemokine receptor CXCR4 to cisplatin and paclitaxel-induced neuropathies." (PMID 22998838, 2012). "A secondary objective was to investigate the potential contribution of alpha-chemokine receptor (CXCR4) signaling to both chemotherapy-induced neuropathy and CB2 agonist efficacy." (PMID 22998838, 2012). "More work is necessary to determine whether CXCR4 signaling contributes to the development of chemotherapy-induced neuropathy." (PMID 22998838, 2012). "We asked whether blockade of CXCR4 signaling with its antagonist AMD3100 would reverse established neuropathy induced by cisplatin and paclitaxel treatment." (PMID 22998838, 2012). "Our study is the first to test the hypothesis that CB2 modulation of chemotherapy-induced neuropathy may interact with CXCR4 signaling." (PMID 22998838, 2012). "Contrary to HIV-associated neuropathy, blockade of CXCR4 signaling by AMD3100 in our study did not inhibit the maintenance of mechanical or cold allodynia evoked by either cisplatin or paclitaxel." (PMID 22998838, 2012). "Chemokine CXC receptor 4 (CXCR4) plays critical roles in DNP, and connexin 43 (CX43), which is also primarily expressed by astrocytes, contributes to the development of neuropathy." (PMID 35799894, 2022). "In antiretroviral toxic neuropathy model, Bhangoo and colleagues have observed up-regulation of SDF1 and CXCR4 mRNA at 7 and 14 days after administration of antiretroviral drug 2, 3-dideoxycytidine, and the enhanced expression of SDF1 was mostly observed in the DRG non-neuronal cells." (PMID 26597700, 2015). "By contrast, CXCR4 signaling does not contribute to the maintenance of chemotherapy-induced established neuropathy or efficacy of AM1710." (PMID 22998838, 2012). "Although there is support for spinal cord-infiltrating CD4+ T lymphocytes in contributing to neuropathic pain due to spinal nerve transection injury, chemotherapy-induced neuropathy does not appear to be influenced by either this cell type or the CXCR4 antagonist AMD3100." (PMID 22998838, 2012). "In addition, our data indicate that neither the maintenance of chemotherapy-induced neuropathy nor the anti-allodynic efficacy of CB2 agonist is dependent upon CXCR4 signaling." (PMID 22998838, 2012).
neuropathy (continued). "However, whether CXCR4 signaling is also involved in chemotherapy-induced neuropathy has not been studied." (PMID 22998838, 2012).
primary immunodeficiency (11 papers, 2016 to 2025). "Warts, hypogammaglobulinemia, infections, myelokathexis (WHIM) syndrome is a rare primary immunodeficiency predominantly caused by heterozygous gain-of-function mutations in CXCR4 C-terminus." (PMID 36089616, 2022). "Specifically, permanent upregulation of CXCR4 leads to myelokathexis and a primary immunodeficiency caused by a hyper functional CXCR4 receptor." (PMID 35531956, 2022). "WHIM (wart, hypogammaglobulinemia, recurrent infections, and myelokthexis) syndrome is an autosomal dominant combined primary immunodeficiency disease caused by loss of function mutations in CXCR4." (PMID 28829353, 2017). "In-depth immune evaluation revealed antibody deficiency syndrome with dysregulated B cell development in family members carrying the CXCR4 variant, whereas P4 – who carried only the NFKB1 variant – showed a profound antibody deficiency and immunologic markers consistent with CVID." (PMID 40909287, 2025). "Primary immunodeficiency, such as is associated with EVER1, EVER2, GATA2, CXCR4, and DOCK8 mutations, as well as combined immunodeficiency, such as in bare lymphocyte syndrome, is associated with extensive HPV infection." (PMID 38637854, 2024). "Primary immunodeficiencies (PIDs) associated with HPV-related disease include inborn errors of GATA, EVER1/2, and CXCR4 mutations, resulting in defective cellular function." (PMID 36960048, 2023). "We report a novel primary immunodeficiency, and a differential molecular diagnosis to CXCR4‐,DOCK8‐,GATA2‐,MAGT1‐,MCM4‐,STK4‐,RHOH‐,TMC6‐, and TMC8‐related diseases." (PMID 27896283, 2016).
uveal melanoma (11 papers, 2007 to 2025). A melanoma derived from melanocytes of the uveal tract. "CXCR4 is expressed in uveal melanoma cells, and it is known that ligand CXCL12 is expressed in the liver." (PMID 38732371, 2024). "Primary tumor uveal melanoma cells express CXC Motif Chemokine Receptor 4 (CXCR4) and C-C Chemokine Receptor 7 (CCR7)." (PMID 38732371, 2024). "In this study, we observed the elevated expression of chemokine receptor 4 (CXCR4) in uveal melanoma (UM) patient liver tissues, and high CXCR4 expression in liver metastases of UM murine models, regardless of the expression levels in the primary tumors." (PMID 35145271, 2022). "A greater liver metastatic number/burden in mice was also observed using CXCR4-positive uveal melanoma cells compared with using CXCR4-negative uveal melanoma cells injected into mice." (PMID 35145271, 2022). "The early detection of uveal melanoma hepatic metastases is achieved by CXCR4 molecular MRI imaging." (PMID 35145271, 2022). "In a previous study, we found that the chemokine receptor CXCR4, a prognostic factor in cutaneous melanoma being involved in angiogenesis and metastasis formation, is commonly expressed in uveal melanoma and correlates to the epithelioid-mixed cell type." (PMID 33330070, 2020). "Cell surface expression of CXCR4 on the 5 uveal melanoma cell lines was verified using Fluorokine: Cytokine Flow Cytometry Reagents for Human SDF-1α Biotin Conjugate (R&D Systems)." (PMID 18001467, 2007). "We sought to characterize the presence of the CXCR4/CXCL12 axis in five uveal melanoma (UM) cell lines in vitro." (PMID 18001467, 2007). "Unpublished data from our laboratory has also shown that CXCR4 was positive in 31 primary human uveal melanoma patient samples." (PMID 17261188, 2007). "This is also supported by a previous study which shows that exposure to low oxygen tension increases migration, invasion and adhesion of Mum2B uveal melanoma cells, activating the expression of CXCR4, angiopoietin-related protein, and pyruvate dehydrogenase kinase 1 in a HIF-1-dependent manner." (PMID 25166211, 2014). "It has also been recently established that high CXCR4 positivity in primary human uveal melanoma specimens correlates with cell type, which is a well established prognostic indicatior for the development of metastatic uveal melanoma." (PMID 18001467, 2007). "CXCR4 could provide early migration of uveal melanoma cells toward the liver." (PMID 38732371, 2024). "Another study on uveal melanoma on paraffin-embedded tissue samples confirmed expression of CCR7 and CXCR4 and found expression of CCR10, primarily in the cytoplasm, for each chemokine receptor; CCL19 demonstrated a moderate expression." (PMID 35203305, 2022). "Analysis of primary uveal melanoma cell lines found elevated expression of CCR7 and CXCR4, although metastatic cell lines had no change in these receptors, and similar results were observed in a nude mouse model." (PMID 35203305, 2022).
adrenocortical carcinoma (10 papers, 2017 to 2024). "We found particularly high expression of CXCR4 on adrenocortical cancer (ACC) metastases." (PMID 29088715, 2017). "In patients affected with adrenocortical carcinoma (ACC), C-X-C motif chemokine receptor 4 (CXCR4) is highly expressed in sites of disease in an ex-vivo setting." (PMID 38896128, 2024). "A recent preclinical study also demonstrated increased ex-vivo CXCR4 expression in tissue specimens of patients affected with adrenocortical carcinoma (ACC)." (PMID 35674738, 2022). "Remarkably, we found very high expression of CXCR4 on some samples of adrenocortical carcinoma (ACC)." (PMID 29088715, 2017). "As an exception to the rule, adrenocortical carcinoma samples displayed negative correlations between CXCR4 expression and levels of infiltrating CD4+ and CD8+ T cells as well as PD-L1." (PMID 36672341, 2023). "In summary, we could demonstrate that CXCR4 and CXCR7 are the most abundant chemokine receptors in adrenocortical carcinoma." (PMID 33281749, 2020). "Therefore, 68Ga-Pentixafor imaging could potentially be used to identify adrenocortical carcinoma patients who would benefit from CXCR4-targeted therapies as not all lesions express CXCR4." (PMID 36140541, 2022).
Alzheimer disease (10 papers, 2012 to 2025). A progressive, neurodegenerative disease characterized by loss of function and death of nerve cells in several areas of the brain leading to loss of cognitive function such as memory and language. "Taken together, these data suggest that targeting these signaling pathways may represent a valid strategy for neurorestorative therapies for HAND and other diseases characterized by spine loss and/or CXCR4 dysregulation, such as Alzheimer’s disease (AD) and schizophrenia." (PMID 31971513, 2020). "The compound’s favorable ranking demonstrates the framework’s ability to identify repurposing opportunities for established drugs, with mechanisms relevant to Alzheimer’s disease pathogenesis through CXCR4-mediated modulation of chemokine signaling pathways implicated in neuroinflammation." (PMID 41155297, 2025). "By utilizing the ROC curve to assess the prognostic value of hub genes in the PPI network, 3 out of 5 shared hub genes, namely, CXCR4, MYH11, and TGFB1, showed potential indications as potential biomarkers for Alzheimer’s disease." (PMID 37705610, 2023).
cognitive deficits (10 papers, 2019 to 2025). "In addition, CXCR4 can be used as an intervention target to reduce cognitive impairment caused by propofol." (PMID 34990302, 2022). "We also demonstrated that 10 Hz rTMS attenuated cognitive deficits and motor impairments in MCAO model rats, and these effects were possibly associated with the activation of the SDF‐1α/CXCR4 axis." (PMID 41355332, 2025). "Among these, Cxcl12 and CxCr4 stand out, as dysregulation of the CXCL12 ligand/CXCR4 receptor axis has been implicated in the cognitive deficits associated with several neurodegenerative diseases." (PMID 40498000, 2025). "CXCL12-dependent adult neurogenesis and synaptic plasticity in the dentate gyrus is involved in learning and memory, as wild-type mice treated with a CXCR4 antagonist show cognitive impairment." (PMID 35821178, 2022). "Furthermore, recent investigations have demonstrated that hsa-mir-106a-5p which based on our results is linked to (TGFB1, ITGB1, and CXCR4), reduces the level of VEGFA, a protective factor against cognitive impairment in AD patients." (PMID 37705610, 2023). "In HIV+ opioid users, release of IRP control coupled with inflammatory and oxidative stress response pathways that increase FHC transcript expression may further increase FHC levels, resulting in more robust CXCR4 inhibition, dendritic spine deficits, and cognitive impairment." (PMID 31300544, 2019). "Moreover, chronic administration of a CXCR4 antagonist (AMD3100) results in impaired learning and memory in young non-transgenic mice, thus supporting the hypothesis that low levels of CXCL12/CXCR4 are linked to cognitive deficits." (PMID 31231219, 2019). "The hippocampal expression of both CXCL12 and CXCR4 were decreased in Tg2576 mice at 6 and 12 months of age as compared to age-matched non-transgenic animals; this was paralleled with cognitive impairment." (PMID 35821178, 2022). "More recently, the ratio between C-X-C chemokine receptor type 4 (CXCR4)+ harmful and hyperactive neutrophils to CD62L+ senescent neutrophils and the levels of ROS in blood were found significantly higher in AD patients with severe dementia when compared to mild cognitive impairment (MCI) patients." (PMID 35844591, 2022).
esophageal squamous cell carcinoma (10 papers, 2006 to 2023). Esophageal squamous cell carcinoma (ESCC) is a type of esophageal carcinoma (EC) that can affect any part of the esophagus, but is usually located in the upper or middle third. "The expression of CXCR-4 was found to be associated with the grade of esophageal squamous cell carcinoma." (PMID 34885003, 2021). "In this survey, we aimed to detect the expression levels of MIF and CXCR4 in different cell populations of tumor microenvironments and their association with survivals of patients with esophageal squamous cell carcinoma (ESCC)." (PMID 23497377, 2013). "We found overexpression of CXCR4 after NRCHT + R compared to R alone in both esophageal SCC and AC patients." (PMID 35993091, 2022). "The overall expression rate for CXCR4 in esophageal squamous cell carcinoma was 94.1%." (PMID 17176471, 2006). "These authors have demonstrated that positive CXCR4 expression in the primary tumor post pre-operative chemoradiotherapy correlates very strongly with progression to distant metastasis, which provides clinicians with an independent prognostic factor for esophageal squamous cell carcinomas." (PMID 18001467, 2007).
follicular lymphoma (10 papers, 2010 to 2025). Follicular lymphoma is a form of non-Hodgkin lymphoma characterized by a proliferation of B cells whose nodular structure of follicular architecture is preserved. "The interaction between C-X-C motif chemokine receptor 4 (CXCR4) expressed by follicular lymphoma (FL) cells with CSC-like activities and CXCL12, which is secreted by follicular DCs, facilitates chemotherapy resistance and tumorigenicity." (PMID 38164743, 2023). "Strong CXCR4 expression is also detected in follicular lymphoma with both flow cytometry and immunohistochemical analysis." (PMID 32757068, 2020). "They demonstrated a significantly lower level of CXCR4 expression in follicular lymphoma, in contrast to B-CLL, which was characterized by the high expression of that receptor." (PMID 24859274, 2014). "CXCR4 mutations are essentially unique to WM, as they have not been described so far in other malignancies, except for several cases of patients affected by follicular lymphoma." (PMID 32784523, 2020). "Recently, the CXCL12/CXCR4 axis was reported to function through p38 MAPK signaling to drive the progression and metastasis of various cancers, including follicular lymphoma and lung, thyroid, colorectal and breast carcinomas." (PMID 31434952, 2019). "We determined the expression levels of CXCR4, CXCR7, and their ligand CXCL12 in NGCB- and GCB-DLCBLs consisting of primary and transformed follicular lymphomas (n = 71 in total) and germinal center B cells (GC-B, n = 5) serving as non-neoplastic controls by using RQ-PCR." (PMID 31554271, 2019).
infarction (10 papers, 2014 to 2023). A localised pathological necrosis of tissue resulting from obstruction of the blood supply usually by a thrombus, an embolus, or vascular torsion. "Overexpression of CXCR4 in MSCs resulted in decreased LV remodeling and enhanced LV function, indicating that modifying the CXCR4 expression level was beneficial for post-infarction myocardial repair." (PMID 35130979, 2022). "CXCR4 signal intensity in the kidneys 7d after infarction, however, was inversely proportional to late cardiac function (r = -0.79, p < 0.01)." (PMID 34335975, 2021). "The SDF-1/CXCR4 axis seems to be a novel therapeutic approach to improve post-infarction therapy by attracting circulating stem cells to the site of injury where they differentiated into cardiac cells in the infarcted heart." (PMID 24705272, 2014). "To determine whether either SDF-1 or CXCR4 expression may be altered by amlodipine, we finally examined mRNA levels in the border zone around the infarction sites of hearts." (PMID 27243031, 2016). "The CXCR4/SDF-1 axis plays a key role in remodeling blood flow after infarction." (PMID 24505417, 2014). "Elevated SDF‐1 expression in the conditioned medium following pre-treatment with bFGF and 5-aza,could increase C‐X‐C chemokine receptor type 4 (CXCR‐4) on the surface of MenSCs that can lead to efficacious migration of stem cells to the site of infarction and/or ischemic myocardium." (PMID 36587199, 2022). "Reperfused AMI led to an increase in CXCR4, but not SDF-1α, at 3 days post-infarction, with moderate enhancement of circulating CD34+ counts." (PMID 28299177, 2016).
kidney damage (10 papers, 2018 to 2026). "In an adriamycin (ADR)-induced nephropathy model, increased CXCR4 expression was found to be associated with podocyte injury, and blockade of this pathway reduced podocyte oxidative stress, proteinuria, and fibrosis." (PMID 41601976, 2026). "The CXCL12/CXCR4 pathway can promote chronic allogeneic nephropathy progression and fibrosis by recruiting bone marrow-derived cells to the kidney." (PMID 39192987, 2024). "In CKD mice and humans with a variety of nephropathies, CXCR4 was dramatically up‐regulated in tubules, with a concomitant activation of β‐catenin." (PMID 32119183, 2020). "In summary, the present study firstly provides the data that CXCR4/TXNIP is involved in the modulation of the kidney damage via directly regulating NLRP3 inflammasome." (PMID 29849929, 2018). "To study a potential involvement of β-arrestin-1 in proteinuric kidney diseases, we examined its expression in the nephropathies induced by ADR or chronic infusion of angiotensin II, which are associated with increased levels of oxidative stress and CXCR4 8,31,32." (PMID 34976212, 2022). "A higher percentage of CD34+ CXCR4+ cells may which help by homing-in on the kidney vasculature to repair the endothelial dysfunction present and thereby help prevent progressive kidney damage." (PMID 29724198, 2018). "However, in the present study, renal CXCR4 signal at MI+7d emerged as a stronger predictor for later adverse cardiac functional outcome relative to the infarct signal at the same day post-MI, potentially reflecting a different timeframe to the kidney damage relating to cardiac dysfunction." (PMID 34335975, 2021). "In the UUO nephropathy mouse model, CXCR4 is significantly upregulated, and the nonpeptide CXCR4 antagonist AMD3100 blunts the UUO-induced fibrotic response." (PMID 35015734, 2022).